KCNQ1 (potassium voltage-gated channel subfamily Q member 1)
Diseases named in the same sentence as KCNQ1 in open-access papers (continued):
Sharing a sentence is not in itself a finding about the gene and the disease.
Beckwith-Wiedemann syndrome (9 papers, 2010 to 2025). Beckwith-Wiedemann syndrome (BWS) is a genetic disorder characterized by overgrowth, tumor predisposition and congenital malformations. "Disrupted imprinting caused by mutations in the KCNQ1 gene cause Beckwith-Wiedemann syndrome (BWS), which predisposes to cancer, and KCNQ1 knockout predisposes to gastric metaplasia." (PMID 20625512, 2010). "In contrast, in Beckwith-Wiedemann syndrome, an IGF2 gene polymorphism has been associated with loss of imprinting of the maternal allele-specific methylation of the KCNQ1 gene." (PMID 22022277, 2011). "In the Beckwith-Wiedemann syndrome (BWS) group, patients 4 and patient 5 displayed hypomethylation in the KCNQ1 control region, which is observed in approximately 60% of BWS cases." (PMID 40730975, 2025). "CDKN1C is implicated in syndromes associated with intrauterine growth restriction (IUGR) (IMAGE syndrome) and over-growth (Beckwith-Wiedemann syndrome); one of the birth weight SNPs is located 47 146 bp from this gene within an intron of KCNQ1, which is not linked to DDs." (PMID 33682876, 2021). "These functional associations of IGF2 and KCNQ1 rely on publications reporting how a differentially methylated region in KCNQ1 controls imprinted expression of other genes in the neighborhood and about epigenetic abnormalities in the IGF2/H19 region of Beckwith-Wiedemann syndrome patients." (PMID 23226257, 2012). "Initial studies have reported altered chromatin structural interactions within the KCNQ1 and IGF2-H19 domains in the growth disorders Beckwith-Wiedemann Syndrome (BWS) and Silver-Russell Syndrome (SRS)." (PMID 34338292, 2021).
Sinus bradycardia (9 papers, 2016 to 2024). Bradycardia related to a mean resting sinus rate of less than 50 beats per minute. "The sinus bradycardia that is frequently observed in heterozygous gain-of-function mutations in KCNQ1 can be explained by the slowing effect of such mutations on the intrinsic pacemaker activity of human SAN pacemaker cells, in particular under a vagal tone." (PMID 37108427, 2023). "The simulations substantiated a causative link between the KCNQ1 V141M mutation and an AF/sinus bradycardia phenotype which has been observed clinically." (PMID 30337886, 2018). "Clinical studies have reported that the KCNQ1 mutation can cause sinus bradycardia." (PMID 39723092, 2024). "However, gain-of-function mutations in KCNQ1 have also been associated with sinus bradycardia, while the affected patients showed normal or even prolonged QT intervals." (PMID 37108427, 2023). "In addition, the effects of several gain-of-function KCNQ1 mutations (V141M, R231C, and V241F) on sinus bradycardia have recently been explored using human in silico models of the sinus node (SN)." (PMID 30967788, 2019). "Many KCNQ1 mutations exist and some are associated with sinus bradycardia." (PMID 30123799, 2018). "Some of these gain-of-function mutations are additionally associated with sinus bradycardia [S140G, V141M, R231C, V241F, and F279I], and paradoxically, some KCNQ1 gain-of-function mutations have been linked to QT prolongation (borderline LQT) [S140G, Q147R, R231C and R231H]." (PMID 30967788, 2019). "Another variant, KCNQ1 c.1265del (p.Lys422fs), first reported in 1997, has appeared in patients with LQTS or sinus bradycardia in different studies." (PMID 37568094, 2023). "For example, the A341V mutation in KCNQ1 may result in sinus bradycardia, but may also occur in absence of baseline HR changes compared to non-carriers." (PMID 30123799, 2018).
breast carcinoma (8 papers, 2018 to 2024). "The increased allelic imbalance in the BRCA1 gene is associated with increased breast cancer risk and SNPs (single nucleotide polymorphsims) on the mutated allele of KCNQ1, causing allelic imbalance leading to a less severe form of LQT1." (PMID 32392813, 2020). "We discovered and validated that peripheral blood DNA methylation of KCNQ1, KCNQ1OT1, and PHLDA2 at chromosome 11p15.4-15.5 is associated with breast cancer susceptibility." (PMID 35681632, 2022). "It has been shown in previous work to function as a cis-silencer of the imprinted KCNQ1 cluster and to be involved in the metastasis and proliferation of various tumors, such as hepatocellular carcinoma, cholangiocarcinoma, ovarian and breast cancer tumors." (PMID 34630508, 2021). "Of these, three genes, POM121L2, KCNQ1, and CLEC4C, harbored significant methylation changes consistent with their differential expression in breast cancer." (PMID 33113958, 2020). "Of these, three genes, namely POM121L2, KCNQ1, and CLEC4C, harbored significant methylation changes consistent with their differential expression in breast cancer." (PMID 33113958, 2020).
catecholaminergic polymorphic ventricular tachycardia (8 papers, 2016 to 2025). Catecholaminergic polymorphic ventricular tachycardia (CPVT) is a severe genetic arrhythmogenic disorder characterized by adrenergically induced ventricular tachycardia (VT) manifesting as syncope and sudden death. "Targeted genetic testing includes the three genes linked to long QT syndrome (LQTS), namely KCNQ1, KCNH2, and SCN5A, the latter also causing Brugada syndrome (BrS), in addition to the RYR2 gene, which is linked to catecholaminergic polymorphic ventricular tachycardia (CPVT)." (PMID 36643077, 2023). "Molecular autopsies mainly include the screening of the genes known to be involved in cardiac arrhythmias, such as KCNQ1, KCNH2, and SCN5A, which are associated with long QT syndrome, and RYR2, which is associated with major catecholaminergic polymorphic ventricular tachycardia (CPVT)." (PMID 37372445, 2023).
dilated cardiomyopathy (7 papers, 2020 to 2025). Cardiomyopathy which is characterized by dilation and contractile dysfunction of the left and right ventricles. "Rare diseases (monogenic), such as hypertrophic cardiomyopathy (e.g., MYBPC3, MYH7 mutations), dilated cardiomyopathy (LMNA, RBM20), or inherited arrhythmias (KCNQ1, RYR2), are often caused by single, well-characterized mutations." (PMID 40465697, 2025).
Gestational Diabetes Mellitus (7 papers, 2015 to 2025). "KCNQ1 is also an established T2D risk factor and has been associated with gestational diabetes." (PMID 26789123, 2016). "However, there is limited data regarding the association between KCNQ1 gene polymorphisms and gestational diabetes mellitus (GDM) susceptibility in China." (PMID 40671906, 2025). "KCNQ1 rs2237892, which alters pancreatic β-cell function, is the most well-known susceptibility SNP for T2DM and gestational diabetes mellitus in the Asian population." (PMID 34750480, 2021).
gout (7 papers, 2017 to 2019). A condition characterized by painful swelling of the joints, which is caused by deposition of urate crystals. "In the Dakotas, we observed marginal association of SU with rs179409 of potassium channel, voltage gated KQT-like subfamily Q, member 1 (KCNQ1) gene, which has been shown to associate with gout and hyperuricemia." (PMID 31784582, 2019). "The GWAS in a Han Chinese male cohort showed that rs179785 of the KCNQ1 gene was associated with gout." (PMID 30123371, 2018). "Genome-wide association studies (GWASs) have explored many genes associated with gout, for instance, ABCG2, PKD2, SLC2A9, KCNQ1, SLC22A12 and SLC17A1 for gout disease among individuals of European descent." (PMID 30899057, 2019). "We genotyped the variants of RFX3 (rs12236871), KCNQ1 (rs179785) and BCAS3 (rs11653176) in 723 Japanese clinically defined gout cases and 913 controls by TaqMan method." (PMID 29879923, 2018). "The Chinese GWAS used hyperuricaemic controls in follow-up testing to demonstrate that the newly discovered loci (BCAS3, RFX3 and KCNQ1) are likely to be involved in pathways leading to presentation with gout in people with hyperuricaemia." (PMID 28566086, 2017). "The potential role of candidate genes located at these novel loci in gout is not yet clear, although the KCNQ1 association is notable." (PMID 28566086, 2017). "A recent genome-wide association study (GWAS) of gout identified three new loci for gout in Han Chinese: regulatory factor X3 (RFX3), potassium voltage-gated channel subfamily Q member 1 (KCNQ1), and breast carcinoma amplified sequence 3 (BCAS3)." (PMID 29879923, 2018).
Hypoglycemia (7 papers, 2017 to 2024). A decreased concentration of glucose in the blood. "Consistent with our findings, postprandial hyperinsulinaemia and hypoglycaemia symptoms attributable to loss of KCNQ1 function were reported in a study of 14 patients aged over 40 years." (PMID 39055936, 2024). "The variants that cause the cardiac phenotype of LQTS1 (KCNQ1) are also expressed in pancreatic islet cells and may predispose individuals to hypoglycemia." (PMID 38884101, 2024). "Given that those with loss of function variants in KCNQ1 may be prone to post-prandial hypoglycemia due to increased insulin release from the pancreas, increased vigilance is warranted when prescribing beta-blockers to those with both KCNQ1 variants and the CPT1A p.P479L variant." (PMID 38884101, 2024). "These include KCNQ1 p.L353L, a synonymous splice site variant and modifier of the LQTS phenotype, ANK2 p.S646F, a variant associated with structural heart disease and an adult onset form of LQTS, and CPT1A p.P479L, a variant associated with infant death and hypoglycemia." (PMID 38884101, 2024).
torsades de pointes (7 papers, 2008 to 2022). A malignant form of polymorphic ventricular tachycardia that is characterized by heart rate between 200 and 250 beats per minute, and qrs complexes with changing amplitude and twisting of the points. "The downregulation of several key genes encoding subunits of cardiac ion channels we observed such as KCNQ1, KCNH2, and CACNA1C, is in line with findings that show QT prolongation and torsade de pointes in patients treated with protease inhibitors (PI), such as lopinavir and ritonavir." (PMID 35686037, 2022). "In humans, drug effects on hERG, SCN5A (Nav1.5), KCNQ1/MinK and KCND3/KChiP2 (Kv4.3) channels often lead to Long QT syndrome (LQTS) or Short QT syndrome (SQTS), including Torsade de Pointes (TdP) arrhythmias, fraught with ventricular fibrillation and ultimately death." (PMID 22039467, 2011).
ventricular fibrillation (7 papers, 2018 to 2025). A disorder characterized by an electrocardiographic finding of a rapid grossly irregular ventricular rhythm with marked variability in QRS cycle length, morphology, and amplitude. "Many rotors and their high rotational rates in KCNQ1 S140G mutation can induce difference in systolic timing among ventricular tissue (ventricular dyssynchrony), which can reduce ventricular pumping performance during ventricular fibrillation." (PMID 30108508, 2018).
cardiac arrest (6 papers, 2014 to 2025). Cessation of breathing and/or cardiac function. "For instance, the pathogenic variant KCNQ1 A341V is associated with clinical severity, being 80% of patients symptomatic and with over 30% of them experiencing cardiac arrest or sudden death." (PMID 33256261, 2020). "The patient is heterozygous for the KCNQ1 variant and suffered from syncopes and seizures since the age of 13 and survived a sudden cardiac arrest at the age of 31, at a family celebration (without beta-blocker) which resulted in severe brain damage." (PMID 36674868, 2023).
Hyperinsulinemia (6 papers, 2017 to 2026). An increased concentration of insulin in the blood. "Recently, individuals with mutations in KCNQ1, encoding Kv 7.1, and KCNH2 (hERG), coding for Kv 11.1, were found to experience episodes of hyperinsulinemia and hypoglycemia after meals." (PMID 40650956, 2025).
Stroke (6 papers, 2016 to 2025). Sudden impairment of blood flow to a part of the brain due to occlusion or rupture of an artery to the brain. "Mutant ventricles exhibited similar stroke volumes and stroke work levels under the KCNQ1 S140G mutation and WT conditions, but consumed significantly less contractile ATP under the former condition." (PMID 30108508, 2018).
sudden infant death syndrome (6 papers, 2008 to 2024). Unexpected death in infancy which remains unexplained following autopsy, review of the medical history, and investigation of the death circumstances and death scene. "Previous studies have shown that KCNQ1 variants led to cardiac long-QT syndrome and sudden infant death syndrome 13,14." (PMID 24373634, 2014). "Another variant in KCNQ1, p.(Ile274Val) -rs199472728, CM070181-, was identified in a sudden infant death syndrome (SIDS) case." (PMID 31315195, 2019). "Mutations in the KCNQ1 gene (also known as KvLQT1 or Kv7.1) are associated with Jervell and Lange-Nielsen (JNL) syndrome, the phenotypes of which include congenital deafness and long QT intervals in the cardiogram, as well as sudden infant death syndrome and Romano–Ward syndrome." (PMID 26084842, 2015).
Bradycardia (5 papers, 2017 to 2023). A slower than normal heart rate (in adults, slower than 60 beats per minute). "The use of drugs with a negative chronotropic effect, such as beta-blockers, should therefore be reviewed and device implantation considered for KCNQ1 gain-of-function mutation carriers that present with bradycardia." (PMID 30967788, 2019). "AC9 is proposed to regulate PKA phosphorylation of KCNQ1 via its scaffolding to Yotiao4, however, the interpretation of a bradycardia phenotype is complicated in mice." (PMID 28717248, 2017). "The AF susceptibility allele identified in our Utah family, KCNQ1 R231H, was previously reported in 5 smaller families of Northern European descent, some of whom also manifested LQTS and fetal bradycardia phenotypes." (PMID 34750360, 2021). "To understand why the carriers of KCNQ1-G229D described in our study and those reported by do not present with bradycardia, we used a population of human SN models to explore the effects of heterogeneity in ion channel expression." (PMID 30967788, 2019).
gingival fibromatosis (5 papers, 2017 to 2023). "The two heterozygous KCNQ1 missense variants, R116L and P369L, cause an allelic disorder characterized by pituitary hormone deficiency and maternally inherited gingival fibromatosis." (PMID 36077086, 2022). "The current work was sparked by our recent finding which showed that two specific mutations in KCNQ1, p.(Arg116Leu) and p.(Pro369Leu), underlie growth hormone deficiency and maternally inherited gingival fibromatosis." (PMID 29740400, 2018). "Here, in families with growth retardation and gingival fibromatosis, the authors identify mutations in the potassium channel gene KCNQ1 that cause electrophysiological aberrations and altered ACTH secretion in vitro." (PMID 29097701, 2017). "Recently, two specific autosomal dominant KCNQ1 missense variants, R116L and P369L, have been shown to underlie an allelic disorder characterized by growth hormone deficiency and maternally inherited gingival fibromatosis." (PMID 36077086, 2022). "We recently reported that two specific mutations in KCNQ1, a gene encoding the alpha subunit of a voltage-gated K+ channel (Kv7.1), result in a gain-of-function in patch clamp analyses and cause pituitary hormone deficiency and maternally inherited gingival fibromatosis." (PMID 29740400, 2018). "Two missense mutations in KCNQ1, an imprinted gene that encodes the alpha subunit of the voltage-gated potassium channel Kv7.1, cause autosomal dominant growth hormone deficiency and maternally inherited gingival fibromatosis." (PMID 29740400, 2018). "In conclusion, our results reveal a role for the KCNQ1 potassium channel in the regulation of human growth, and show that growth hormone deficiency associated with maternally inherited gingival fibromatosis is an allelic disorder with cardiac arrhythmia syndromes caused by KCNQ1 mutations." (PMID 29097701, 2017). "Expression of KCNQ1 has recently been reported in human gingival fibroblasts and KCNQ1 was found to be upregulated in gingival tissue from individuals with non-syndromic hereditary gingival fibromatosis." (PMID 36077086, 2022). "We identified two missense mutations in KCNQ1 to underlie childhood onset of GHD and maternally inherited gingival fibromatosis." (PMID 29097701, 2017).
hepatocellular carcinoma (5 papers, 2020 to 2024). A malignant tumor that arises from hepatocytes. "However, the KCNQ1 deficiency was observed in hepatocellular carcinoma cells and tissue, compared with the corresponding normal tissue, and it was identified as a prognostic predictor for a poor survival in hepatocellular carcinoma." (PMID 38807370, 2024). "DNA hypermethylation of KCNQ1 promoter has been shown to downregulate KCNQ1 expression in hepatocellular carcinoma (HCC)." (PMID 32850327, 2020). "Another study described the same function of KCNQ1 in Hepatocellular Carcinoma (HCC)." (PMID 33117152, 2020).
intestinal tumors (4 papers, 2017 to 2024). "In human CRC, low KCNQ1 expression was associated with poor survival and mutation of the murine homologue Kcnq1 increased the risk for intestinal tumors." (PMID 28060743, 2017).
long QT syndrome 3 (4 papers, 2017 to 2025). An autosomal dominant condition caused by mutation(s) in the SCN5A gene, encoding sodium channel protein type 5 subunit alpha. "Moreover, the identified monoclonal KCNQ1 antibody suppresses arrhythmias in a cellular model of long QT syndrome type 3, holding promise as a first-in-class antiarrhythmic immunotherapy." (PMID 37947435, 2023).
schizophrenia (4 papers, 2016 to 2025). A major psychotic disorder characterized by abnormalities in the perception or expression of reality. "Additionally, KCNQ1, a known risk gene for schizophrenia, was elevated in FES patients and CUS + repMg-exposed animals, possibly as a compensational mechanism." (PMID 37771931, 2023).
sudden cardiac arrest (4 papers, 2017 to 2022). Unexpected rapid natural death due to cardiovascular collapse within one hour of initial symptoms. "This suggests that the KCNQ1 S140G mutation increases the risk of death by sudden cardiac arrest." (PMID 30108508, 2018). "Among these genetic anomalies, only four variants, i.e., KCNQ1, KCNE1, SCN1A, and CACNA1C, were previously associated with SUDEP or other disorders associated with sudden cardiac death (SCD)." (PMID 29261713, 2017). "Sudden cardiac arrest during sleep has also been reported for a carrier of KCNQ1-R231H." (PMID 30967788, 2019).
arrhythmogenic right ventricular cardiomyopathy (3 papers, 2021 to 2025). "The most frequent in the ACMG SFs were gene/disease and frequency TTN DCM (four times); KCNQ1 LQTS (three times); MYBPC3 HCM (two times); TMEM43 arrhythmogenic right ventricular cardiomyopathy (two times); PALB2 HBC (two times); and RYR1 MH (two times)." (PMID 36635046, 2023).
Epileptic encephalopathy (3 papers, 2021 to 2024). A condition in which epileptiform abnormalities are believed to contribute to the progressive disturbance in cerebral function. "In one of the individuals, a patient with epileptic encephalopathy and a family history of long QT and with a previously identified KCNQ1 pathogenic variant, we also identified an HPDL causative variant [p.(Ala116Cysfs*81)], leading to a dual diagnosis." (PMID 37152996, 2023).
esophageal cancer (3 papers, 2021 to 2022). A primary or metastatic malignant neoplasm involving the esophagus. "Furthermore, it has been shown that miR-483-5p facilitates esophageal cancer proliferation, migration, and invasion by silencing potassium voltage-gated channel subfamily Q member 1 (KCNQ1)." (PMID 35883677, 2022).
Hypokalemia (3 papers, 2017 to 2021). An abnormally decreased potassium concentration in the blood. "In the context of hypokalemia, KCNQ1/hERG co-expression slowed the internalization of mature, i.e. cell-surface expressed, hERG channels whereas KCNQ1 alone is not sensitive to hypokalemia." (PMID 29089904, 2017).